GBP7 (guanylate binding protein 7)
Description:
Interferon (IFN)-inducible GTPase that plays important roles in innate immunity against a diverse range of bacterial, viral and protozoan pathogens (By similarity). Hydrolyzes GTP to GMP in two consecutive cleavage reactions and predominantly uses GTP and not GDP or GMP as the substrate (By similarity). Following infection, recruited to the pathogen-containing vacuoles or vacuole-escaped bacteria and acts as a positive regulator of inflammasome assembly by promoting the release of inflammasome ligands from bacteria (By similarity). Acts by promoting lysis of pathogen-containing vacuoles, releasing pathogens into the cytosol (By similarity). Following pathogen release in the cytosol, promotes recruitment of proteins that mediate bacterial cytolysis: this liberates ligands that are detected by inflammasomes, such as lipopolysaccharide (LPS) that activates the non-canonical CASP4/CASP11 inflammasome or double-stranded DNA (dsDNA) that activates the AIM2 inflammasome (By similarity). Also promotes IFN-gamma-mediated host defense against bacterial infections by regulating oxidative responses and bacteriolytic peptide generation (By similarity). May help to assemble NADPH oxidase on phagosomal membranes by acting as a bridging protein between NADPH oxidase cytosolic subunits NCF2-NCF4 and the membrane subunits CYBA-CYBB (By similarity). Participates along with GBP1 in trafficking monoubiquitinated protein cargo to autolysosomes for generating ubiquitin-derived antimicrobial peptides (By similarity). Facilitates influenza A virus replication by inhibiting the activation of NF-kappaB and JAK-STAT signaling pathways and the expression of type I, type III interferons and pro-inflammatory cytokines. Confers protection to several pathogens, including the bacterial pathogens Listeria monocytogenes and Mycobacterium bovis BCG as well as the protozoan pathogen Toxoplasma gondii (By similarity). Required for disruption of the parasitophorous vacuole formed following T.gondii infection and subsequent killing of the parasite (By similarity).
Synonyms: GBP4L; FLJ38822
Tractability: No criterion of Open Targets' tractability assessment is met for any kind of drug.
Gene: Protein-coding gene on chromosome 1 (89,131,742 to 89,176,062, reverse strand). Ensembl gene ENSG00000213512.
Subcellular location: Cytoplasmic vesicle membrane
Pathways (Reactome):
Immune System: Interferon gamma signaling
Gene Ontology:
Molecular function: protein binding; GDP phosphatase activity; GTP binding; GTPase activity
Biological process: defense response to virus; negative regulation of cytokine production; negative regulation of receptor signaling pathway via JAK-STAT; negative regulation of type I interferon production; negative regulation of type III interferon production; positive regulation of viral genome replication; regulation of canonical NF-kappaB signal transduction; cellular response to type II interferon; cytolysis in another organism; defense response to bacterium; defense response to Gram-positive bacterium; defense response to protozoan
Cellular component: cytoplasmic vesicle; cytoplasmic vesicle membrane
Genetic constraint (gnomAD): Loss-of-function variants: 38 observed, 57.4 expected, observed/expected ratio (o/e) 0.66, 90% interval 0.51 to 0.87. The upper end of that interval is the gene's LOEUF score, 0.87, which puts it in group 3 of 6, group 1 being the genes least tolerant of losing a copy. Missense variants: 715 observed, 767.94 expected, observed/expected ratio (o/e) 0.93, 90% interval 0.88 to 0.99. Synonymous variants: 267 observed, 283.86 expected, observed/expected ratio (o/e) 0.94, 90% interval 0.85 to 1.04.
Homologues: Orthologues: chimpanzee GBP7 (99% identical), macaque GBP7 (91% identical), Drosophila melanogaster atl (17% identical). Paralogues in human: GBP4 (76% identical), GBP6 (68% identical), GBP2 (51% identical), GBP3 (50% identical), GBP1 (50% identical), GBP5 (47% identical), ATL2 (20% identical), ATL1 (18% identical), ATL3 (17% identical), RNF112 (13% identical).
Diseases named in the same sentence as GBP7 in open-access papers:
GBP7 is named in the same sentence as 13 diseases in open-access papers, as found by Europe PMC text mining. Sharing a sentence is not in itself a finding about the gene and the disease. The quoted sentences say what the papers report.
anaemia (1 paper, 2014). "Even so, a number of marginal susceptibility genotype associations were also observed between specific gene mutations and anaemia (GBP7), CM (CD40LG), hyperparasitaemia (NOS2), hyperpyrexia (CD36, CD40LG, G6PD), SMA (EMR1) and UM (NOS2, EMR1)." (PMID 24934404, 2014). "Nevertheless, a number of marginal protective genotype associations were also observed between specific gene mutations and anaemia (CFTR, GNAS), hyperparasitaemia (DERL3, GBP7), hyperpyrexia (GBP7, ABO) and SMA (HbS, ADCY9)." (PMID 24934404, 2014).
endotoxemia (1 paper, 2018). "Interestingly, we found that GBP2 deficiency fails to significantly inhibit caspase-11-dependent immune responses in endotoxemia; whereas genetic deletion of GBP1, GBP2, GBP3, GBP5 and GBP7 simultaneously blocked endotoxemia-induced caspase-11 activation." (PMID 30587103, 2018).
liver cancer (1 paper, 2023). An epithelial or non-epithelial malignant neoplasm that arises from the liver. "The single‐cell data also revealed that GBP6 was not expressed in the liver and the expression of GBP7 in liver cancer immune cells was extremely low." (PMID 37551111, 2023).
lymph node metastasis (1 paper, 2022). "Low GBP6 expression was correlated with poor cell differentiation and lymph node metastasis in tongue squamous cell carcinoma (TSCC), and low GBP7 expression was linked with short OS in HNSC patients." (PMID 35222540, 2022).
Sepsis (1 paper, 2022). Sepsis is defined as life-threatening organ dysfunction caused by a dysregulated host response to infection. "The gene expression of GBP2, GBP6, and GBP7 in the Sham group was significantly higher than that in the sepsis group." (PMID 36405762, 2022).
viral infection (1 paper, 2016). "Genes in this signature code for proteins that are viral infection restricting factors (e.g. Ifitm1, Ifitm3, Gbp7), that protect against cellular or environmental stress (e.g. Abcb1a, Car2, Ern1, Serpina3g) or that regulate immune activation processes (e.g. Fgl2, Anxa1, Havcr2)." (PMID 27883012, 2016).
infection (15 papers, 2015 to 2025). The state of being infected such as from the introduction of a foreign agent such as serum, vaccine, antigenic substance or organism. "Mice lacking GBP2, GBP5, or multiple GBPs on chromosome 3 (GBP2, GBP2b (GBP1), GBP3, GBP5, GBP7) were significantly more susceptible to infection, revealing a critical role for these proteins in restricting bacterial infection." (PMID 32150572, 2020). "For instance, BECs expressed increased Gbp4 and Gbp2, and LECs expressed increased Gbp4, Gbp2, and Gbp7 upon infection." (PMID 35789215, 2022). "Our data analysis showed that (GBP2, GBP3, and GBP7 in the type I IFN signaling pathway were significantly upregulated after E30 infection." (PMID 36147849, 2022). "Analysing DEGs based on the effect of infection intensity adjusted for genotype effects (IV), we found significant upregulation of GBP7 (log2FC = +19.32, p < 0.001) in hens with higher infection intensity." (PMID 33918448, 2021). "Our findings suggest the activation of GBP7 after ascarid infections, which leads to the assumption that GBPs show strong functional similarities between birds and mammals." (PMID 33918448, 2021). "We identified GBP7 as the major differentially expressed transcript between LD and LB hens when gene abundance was adjusted for infection intensity." (PMID 33918448, 2021). "The expression of Gbp3 and Gbp7 increased following infection with L. mexicana." (PMID 40631203, 2025). "To investigate whether individual GBPs are responsible for IRGB10 recruitment, we overexpressed IRGB10 and one GBP at a time (GBP1, GBP2, GBP3, GBP5 or GBP7) in LA-4 cells followed by infection with F. novicida." (PMID 35906252, 2022). "An important potential candidate gene is GBP7, which has already been described in connection with infections of parasites (T. gondii), bacteria, or Influenza A virus in mice and perhaps has a similar function in ascarid infections in chickens." (PMID 33918448, 2021). "In addition, studies have shown that expression of GBP1-3, GBP5, and GBP7 in mice is significantly upregulated 4 h after infection with B. abortus, with GBP5 expression beginning to rise as early as 2 h post-infection and remaining the highest among all GBPs at each time point." (PMID 40606156, 2025). "Further studies, including groups of uninfected control animals, should particularly focus on the expressions of GBP7, RFK, IRF4, and EPHA3 at several time points following infection." (PMID 33918448, 2021). "Transcriptomic profiling of MPXV-infected MK2 cells at 7 h post-infection further revealed the upregulation of multiple guanylate-binding protein (GBP) family members, including GBP3, GBP5, GBP6, and GBP7, highlighting a broader antiviral gene program downstream of type I IFN–IRF1 signaling." (PMID 41225161, 2025). "Similar to Gbp7, Oas2 could also be induced by IFN and serve a role in host defense against infection." (PMID 36421815, 2022). "Follow-up studies, including groups of uninfected control animals, may specifically focus on analysing GBP7 and IRF4 expression at several time points following infection." (PMID 33918448, 2021). "Expression of Gbp5 was strongly induced upon infection with T. gondii, while Gbp2 and Gbp7 were induced at lower levels, and no substantial change was seen in Gbp1 or Irga6." (PMID 30154263, 2018). "Raymond previously demonstrated that upon IBDV infection, regulatory factors including EIF2AK2, MX, GBP7, and IFIT may trigger the IFIT5-IRF1/3-RSAD5 signalling pathway in DF-1 cells, which potentially restricts viral replication during the early infection stage." (PMID 27816055, 2016). "In addition to the reported regulatory factors including EIF2AK2, MX, OAS*A, GBP7 and IFIT, IBDV infection also triggered a IFIT5-IRF1/3-RSAD5 pathway in the DF-1 cells which potentially restricted the viral replication cycle in the early infection stage." (PMID 26053856, 2015).
infection (continued). "As early as 2 hours post-infection, we observed significantly increased GBP2, GBP5 and GBP7 mRNA levels compared to non-infected cells." (PMID 38404575, 2024).
cancer (3 papers, 2022 to 2026). A tumor composed of atypical neoplastic, often pleomorphic cells that invade other tissues. "By analyzing the mRNA expression of GBPs in pan-cancer, we found that GBP1-5 were highly expressed in tumor tissues, while GBP6 and GBP7 were less expressed." (PMID 36246628, 2022). "Gene set enrichment analysis (GSEA) of cancer hallmarks pathways in neutrophils showed upregulation of IFN-γ response genes in Group 1 compared with Group 2, which is confirmed by higher expression of IFN-γ–inducible guanylate binding proteins (Gbp2, Gbp4, Gbp6, and Gbp7)." (PMID 41165751, 2026).
GBP7 also shares sentences with these, for which no sentence is quoted: malaria (2 papers); tumor (2); bacterial infection (1); head and neck squamous cell carcinoma (1); tongue squamous cell carcinoma (1).